CASR (calcium sensing receptor)
Diseases named in the same sentence as CASR in open-access papers (continued):
Sharing a sentence is not in itself a finding about the gene and the disease.
cancer (continued). "Treatments with Verapamil were also performed in order to evaluate the role of the Calcium-Sensing Receptor (CaSR) in the release of Mn2+ ions out of the cancer cells." (PMID 27995976, 2016). "Over the past 15 years many studies have reported that the CaSR can act to either promote or suppress tumorgenesis and metastasis depending on the cancer type." (PMID 27303307, 2016). "For breast cancer cells it was demonstrated that the elevated Ca2+-release during bone remodeling represents a chemoattractant, which promotes migration of cancer cells to bone via activated CaSR." (PMID 27625611, 2016). "We studied the effect of CaSR on hallmarks of cancer in two CRC cell lines: the Caco2-15 cells representative of differentiated tumors, and the highly malignant HT29 cells representative of undifferentiated tumors." (PMID 25701758, 2015). "We found that the stable over-expression of the functional CaSR affected several hallmarks of cancer cells: reduced growth, increased differentiation and induced apoptosis." (PMID 25701758, 2015). "Additionally, CaSR is involved in the inhibition of apoptosis and the proliferation of cancer cells." (PMID 38920679, 2024). "Therefore, further investigation is required to determine the significance of CaSR in cancer treatment." (PMID 39113697, 2024). "In addition, a high level of extracellular Ca2+ is a driver for bone metastasis in cancers, which expresses the extracellular calcium-sensing receptor (CaSR)." (PMID 37750331, 2023). "Calcium-sensitive receptors (CASR) have a role in malignant tumor bone metastases." (PMID 35655917, 2022). "In addition, cancer cells express the calcium-sensing receptor, which allows the calcium released during bone resorption to further promote cancer cell proliferation and PTHrP release." (PMID 34202300, 2021). "In cancer patients, CASR polymorphisms at rs1801725, but not at rs1801726, are associated with circulating calcium levels, deficiency of humoral immunity, and an increased risk of secondary neoplastic lesions in the lungs and bone." (PMID 34357109, 2021). "The mechanism behind CaSR expression and activation is the result of a very complex combination of multi-receptor actions that affect the entire cellular calcium metabolism and thus, also cancer cell proliferation." (PMID 32931488, 2020). "Therefore, once cancer cells reach bones, exposure to high calcium concentrations in the microenvironment, in turn, activates the CaSR." (PMID 32793401, 2020). "In CLC, the median percentage of CaSR positive cancer cells is less than 1%; it is therefore likely that such a tiny component could not able to influence the proliferation of the neighboring non-NE cancer cells." (PMID 32252342, 2020). "In cancer, CASR expression can be reduced, lost, or become activated." (PMID 31086531, 2019). "Altered methylation has been previously reported in human CASR promoter in a few cancer conditions." (PMID 30975191, 2019). "Furthermore, several studies have shown that down-regulation of CaSR in cancers favours cell transformation." (PMID 29348629, 2018). "Effect of calcium, vitamin D and involvement of the CaSR in development of cancer." (PMID 27803671, 2016). "Since HT29 cells display expression of pluripotency-related genes, we evaluated whether expression of the CaSR could decrease the cancer stem cell-like properties of these cells." (PMID 25879211, 2015). "Manipulation of CaSR expression and chemical modulation of CaSR function in cell lines demonstrates that the CaSR is indeed a functionally relevant target so that strategies aiming at either inducing CaSR expression or positively modulating its function are predicted to reduce cancer incidence." (PMID 25701758, 2015). "CaSR seems to also play a role in cancer progression of other entities." (PMID 24576174, 2014). "Epigenetic silencing of the CaSR could be one reason for reduced expression of the receptor in more advanced cancers and in nearly all lymph node metastases." (PMID 23340319, 2013).
cancer (continued). "CaSR may either impede or facilitate tumorigenesis, contingent upon the specific cancer type." (PMID 38920679, 2024). "Therefore, any changes of pH and ionic strength that occur in cancer cells may affect the activity of the CASR and subsequently affect its capability to integrate several signaling pathways." (PMID 31086531, 2019). "Furthermore, the observed anti-cancer effects associated with vitamin D could, to some extent, be a result of a positive feedback mechanism on the production of VDR and/or CaSR by colorectal mucosa." (PMID 26205949, 2015). "Previous studies have shown that CASR could regulate autophagy in mammalian cells and that activation or overexpression of CASR induced autophagy, whereas inhibition or knockdown of CASR suppressed autophagy, which might be the molecular mechanism by which CASR regulates cancer." (PMID 38509759, 2024). "Calcium ions increased the expression of TRPV4 by VPAC1, CaSR, and Ca2+-activated K+ channels including SK1/3, IK1, and BK in other cancers, but the mechanism of overexpressed TRPV4 in EC still remained elusive." (PMID 33230171, 2020). "This is a preliminary study aimed to address the potential correlation between the different expression level of calcium receptors such as CaSR and TRPV6 and manganese uptake in different cancer animal models." (PMID 32931488, 2020). "In this case the expression level of CaSR and TRPV6 receptors was markedly different, instead of what observed for the other cancer animal models." (PMID 32931488, 2020). "In bone metastatic prostate cells, Ca2+/CaSR upregulates the expression of cyclin D1, a key component of the cell cycle, to support cancer cell growth, but this upregulation is absent in the nonskeletal metastases." (PMID 36071984, 2022). "CaSR induces activation of AKT/β-catenin, leading to cancer metastasis." (PMID 36046433, 2021). "The findings from these previous studies indicate that high doses of NPS-2143 that reduce CaSR expression, as well as activity, may be required for NPS-2143 to be effective in reducing the growth of cancer cells." (PMID 34223822, 2021). "The two other supporting mechanisms for cancer promotion and drug resistance in B16F10 cells include PRP4-induced inhibition of Ca2+ influx through CaSR desensitization and remodeling of the cell actin cytoskeleton by the downregulation of the AC–cAMP–RhoA signaling pathway (Graphical abstract)." (PMID 34209674, 2021). "Potentially the interaction between the variants in CASR and in the CYP27B1 genotypes, which activates the ligand for the CASR promoter, could contribute to the etiology of cancer, however this has not been demonstrated yet." (PMID 32197412, 2020). "However, CaSR is not the only receptor involved in the presence of the altered calcium metabolism in cancer cells, as other calcium receptors or channels can interfere with Ca2+ homeostasis." (PMID 32931488, 2020). "Moreover, current strategies to reduce CaSR activity, rather than protein expression for cancer treatments, may be ineffective." (PMID 34223822, 2021). "CaSR not only plays a pivotal role in mineral homeostasis by regulating PTH and urinary Ca excretion, but also affects noncalcitropic diseases, such as cancer and cardiovascular disease." (PMID 32517664, 2020).
cardiovascular diseases (21 papers, 2013 to 2025). "This review provides an overview of the recent research progress on the various regulatory mechanisms of the CaSR in related cardiovascular diseases and the heart–kidney interaction; the associated common causes are also discussed." (PMID 36231037, 2022). "In addition, the CaSR signaling pathways involved in various common causes of cardiovascular diseases are discussed based on the available data." (PMID 36231037, 2022). "Moreover, it was also demonstrated that multiple regulations of the CaSR, such as upregulation/downregulation, activation/inhibition, mutation, degradation, or limited proteolytic cleavages, promote or prevent related cardiovascular diseases." (PMID 36231037, 2022). "It is important that further work is carried out on the CaSR and proliferation of VSMCs as although current available data may be variable, it does highlight the potential for CaSR therapeutics, whether calcimimetics and/or calcilytics, to reduce proliferation associated with cardiovascular disease." (PMID 39912052, 2025). "Proliferation and calcification of VSMCs are associated with vessel remodeling, changes in contractility, and cardiovascular disease, and there is substantial evidence for a role for the CaSR in these processes." (PMID 39912052, 2025). "CASR is expressed in various cardiovascular cell types and has a crucial role in cardiovascular diseases." (PMID 39774334, 2025). "A role for the CaSR in these processes and development of PAH has been widely studied and probably represents the most comprehensive evidence available that the CaSR is a potential therapeutic target to treat a cardiovascular disease." (PMID 39912052, 2025). "The role of calcium-sensiing receptor (CaSR), among G protein-coupled receptors, in cardiovascular disease processes has been extensively investigated." (PMID 38715976, 2024). "Due to the multiple roles of the CaSR in kidney diseases, it is necessary to understand the potential of targeting the CaSR as a therapeutic approach in cardiovascular disease patients with cardiorenal syndrome." (PMID 36231037, 2022). "The CaSR plays an important role in cardiovascular physiology, and the dysregulation of CaSR signaling participates in cardiovascular diseases." (PMID 36231037, 2022). "We present a general overview of CaSR signaling between the mitochondria, ER, nucleus, lysosome, and proteasomes in related cardiovascular diseases." (PMID 36231037, 2022). "Several researchers have proven the activation of CaSR in the development and progression of cardiovascular diseases." (PMID 33519531, 2020). "Calcium sensing receptor (CaSR) belongs to the G protein-coupled receptor family and plays a key role in Ca2+ homeostasis and in the pathophysiology of cardiovascular disease." (PMID 30906223, 2019). "Recently, considerable focus has been placed on circulating cells, as circulating monocytes, involved in cardiovascular disease and CaSR expression has been demonstrated in circulating monocytes." (PMID 25134967, 2014). "This pro-inflammatory effect of CaSR may also affect adipose tissue, which is a key factor in metabolic cardiovascular disease." (PMID 41208959, 2025). "Summary of studies on CaSR in specific cardiovascular diseases." (PMID 41208959, 2025). "Therefore, Calcium-sensing receptor (CaSR) can serve as an important target for the treatment of cardiovascular diseases." (PMID 41208959, 2025). "However, given the complex relationship between CaSR and cardiovascular disease and the fact that most human diseases interact, combining multiple target drugs is likely the most effective treatment." (PMID 38715976, 2024). "Thereby, the clarification of the cellular signaling of the CaSR may help to treat cardiovascular diseases in the future." (PMID 36231037, 2022).
cardiovascular diseases (continued). "As the CaSR plays diverse and crucial roles in human physiology and pathophysiology, both in calcitropic and non-calcitropic tissues and cells, the drugs targeting the CaSR to treat human diseases, including cardiovascular diseases, have been considered." (PMID 36231037, 2022). "Recently, it has also been suggested that the CaSR mediates the intracellular communications between the endoplasmic reticulum (ER), mitochondria, nucleus, protease/proteasome, and autophagy–lysosome, which are involved in related cardiovascular diseases." (PMID 36231037, 2022). "This is especially fueled by the observation that CaSR is expressed on the surface of vascular and hematopoietic cells, which play a vital role in inflammatory processes and thereby has subsequent repercussions on cardiovascular diseases (CVDs)." (PMID 33804544, 2021). "Overall, we hypothesized that HG can induce EndMT via a CaSR-dependent pathway, which accounts for cardiovascular disease in DM." (PMID 33519531, 2020). "However, due to the highly specific cell-type specificity of CaSR regulation and signaling, the pharmacotherapy of cardiovascular diseases that directly target the CaSR may have adverse effects on other tissues, such as kidney injury." (PMID 36231037, 2022). "This review focuses on the CaSR-mediated intracellular communication in the non-calcitropic cells of the cardiovascular system and calcitropic kidney cells and the diverse regulation of CaSR signaling in protecting or promoting cardiovascular diseases." (PMID 36231037, 2022).
kidney diseases (8 papers, 2010 to 2025). "However, one of the leading treatments for SHPT in advanced renal disease are the calcimimetics (cinacalcet and etelcalcetide), which target the CaSR directly and provide clinically significant reductions in PTH secretion." (PMID 31619668, 2019). "Therefore, CaSR can serve as a therapeutic target for combined heart-kidney diseases." (PMID 41208959, 2025).
genetic disorder (7 papers, 2011 to 2024). "NSHPT, a rare genetic disorder associated with high mortality rates, is often caused by inactivating CaSR gene variants." (PMID 39703927, 2024). "The most common confirmed genetic disorder in our sample was FHH type 1 (due to CASR variants), followed by MEN4 (due to CDKN1B variants)." (PMID 37810884, 2023). "FHH is a genetic disorder frequently caused by inactivating mutations in the CaSR gene." (PMID 39246902, 2024). "CASR gene mutations have been implicated in several rare familial genetic disorders." (PMID 21966463, 2011).
infection (5 papers, 2018 to 2022). The state of being infected such as from the introduction of a foreign agent such as serum, vaccine, antigenic substance or organism. "Rat testicular macrophages showed upregulation of CaSR after infection, associated with increased activation of the NLRP3 inflammasome and release of IL-1β." (PMID 36685206, 2022). "Here, we show that CaSR upregulation after infection in TM in a rat model of UPEC induces the activation of the NLRP3 inflammasome pathway and thereby enhances IL-1β secretion and reduces the testosterone level in the blood." (PMID 33193351, 2020). "Mechanistic analysis using lentivirus infection showed that CaSR overexpression activated the CaMKII and CaN signaling pathways and that this response was enhanced by Iso." (PMID 30364197, 2018). "Elevated calcium concentrations at sites of acute or chronic inflammation or infection may further stimulate CaSR-mediated chemotaxis, particularly of monocytes." (PMID 36685206, 2022).
adenocarcinoma (3 papers, 2015 to 2022). A common cancer characterized by the presence of malignant glandular cells. "The expression of a calcium-sensing receptor (CaSR) in patients with adenocarcinoma leads to higher CatK levels and hormone calcitonin receptors in osteoclasts, which are related to bone matrix degradation." (PMID 36430239, 2022). "Caco2-15 cells, derived from a well-differentiated adenocarcinoma express detectable levels of endogenous CaSR." (PMID 25701758, 2015). "HT29 is a highly malignant, adenocarcinoma-derived cell line with negligible levels of endogenous CaSR expression making these cells a good model to assess whether ectopic CaSR expression and function would restore their sensitivity to the anti-tumorigenic effects of Ca2 +." (PMID 25701758, 2015).
endocrine diseases (3 papers, 2020 to 2026). "CaSR agonists (calcimimetics) or antagonists (calcilytics) may be helpful for management of Ca2+ metabolism in endocrine disorders." (PMID 32659887, 2020).
metabolic disorders (3 papers, 2017 to 2026). "Taken together, these results suggest that HG induces myocardial energy metabolism disorder via decrease of CaSR expression, and activation of gp78-ubiquitin proteasome system." (PMID 28518143, 2017).
Coronary artery (2 papers, 2014 to 2020). "Coronary artery calcium (CAC) and abdominal aortic calcification (AAC) scores were evaluated by computed tomography and an association between these scores and the surface and/or total CaSR expression in circulating monocytes in RA patients was investigated." (PMID 25134967, 2014).
neurological diseases (2 papers, 2019 to 2020). "CaSR is widely expressed in the brain and has emerged as an important signaling pathway in neurological diseases such as Alzheimer’s disease." (PMID 31601786, 2019).
skeletal dysplasia (2 papers, 2018 to 2023). Any Mendelian diseases that affects growth and development of the skeleton. "A notable aspect of this study was the frequency of heterozygous mutations detected in genes previously associated with skeletal dysplasia (NPR2, ACAN, CASR, COMP, and FBN1), confirming the dose effect of cartilage matrix proteins in growth and development." (PMID 37605180, 2023). "Postnatal molecular genetic analysis found no causative variants in CASR, GNA11, APS21, or a 336 gene skeletal dysplasia panel investigated by whole exome sequencing." (PMID 30144375, 2018).
bacterial infections (1 paper, 2021). "For example, Jonathan and colleagues showed that the activation of the CaSR/PLC/IP3R signaling pathway increases NOD1 inflammatory responses after bacterial infections." (PMID 34603302, 2021).
cardiac diseases (1 paper, 2022). "As cited in this review, the pharmaceutical activation or inhibition of the CaSR might be potential therapeutic strategies to prevent or treat vascular or cardiac diseases." (PMID 36231037, 2022).
central nervous system diseases (1 paper, 2022). "The nerve injury and toxic effects of CaSR and TREM-1 have been demonstrated in other central nervous system diseases, but little research has been conducted on EBI after SAH." (PMID 36561497, 2022).
muscular disorders (1 paper, 2021). "Since this is a first study exploring CaSR in healthy human skeletal muscle, future studies should address the same question in the evaluation of CaSR expression in tissues derived from patients with myopathies or other muscular disorders." (PMID 34298895, 2021).
parathyroid gland (1 paper, 2020). "The persistence of these triggers leads to a progressive reduction of calcium-sensing receptors (CaSR) and vitamin D receptors (VDR) expression in parathyroid glands preluding to irreversible parathyroid gland hyperplasia onset." (PMID 32120854, 2020).
skeletal muscle disorder (1 paper, 2021). A disease involving the skeletal muscle tissue. "Considering this information, we hypothesized the presence of GPRC6A, instead of CaSR, in our model, which could be a possible drug target for skeletal muscle disorder." (PMID 34298895, 2021). "Since Ca2+ plays an important role in skeletal muscle development, we have hypothesized that CaSR, along with Ca2+ channels, can have a role in myogenic differentiation, becoming a possible molecular target for skeletal muscle disorders." (PMID 34298895, 2021).
CASR also shares sentences with these, for which no sentence is quoted: Gitelman syndrome (5 papers); hypophosphatemia (5); airway hyperresponsiveness (4); end-stage renal disease (4); acute myocardial infarction (3); autoimmune polyglandular syndrome type 1 (3); bone disorder (3); calcium oxalate kidney stones (3); dementia (3); Familial hypocalciuric hypercalcemia type 3 (3); metastasis (3); osteomalacia (3); autoimmune disorders (2); cardiac arrhythmia (2); colonic adenocarcinoma (2); Hypokalemia (2); idiopathic hypercalciuria (2); metastatic prostate carcinoma (2); polycystic kidney disease (2); polycystic ovarian syndrome (2); psoriasis (2); acrodysostosis (1); acromegaly (1); acute myeloid leukaemia (1); acute pancreatitis (1); Adrenal insufficiency (1); alcohol abuse (1); arteriosclerosis (1); autosomal-dominant tubulointerstitial kidney disease (1); B-cell acute lymphoblastic leukaemia (1).
A further 76 diseases each share a sentence with CASR in 1 paper.